TLR4 (toll like receptor 4)
Diseases named in the same sentence as TLR4 in open-access papers (continued):
Sharing a sentence is not in itself a finding about the gene and the disease.
Obesity (continued). "Proinflammatory cytokines like TNF-α, C-reactive protein, and CD14, a coreceptor of toll-like receptor-4 (TLR4) were reported to be elevated in maternal circulation with obesity." (PMID 39396700, 2024). "Yogurt supplementation, with associated probiotic bacteria, attenuated metabolic endotoxemia and inflammation in mice with obesity likely through reduced activation of the TLR4 signaling pathway." (PMID 38978699, 2024). "In this study, wild-type (WT) and TLR4 gene knockout (TLR4−/−) mice were used for obesity and diabetes modeling." (PMID 38275739, 2024). "The different changes in body weight and blood glucose in WT and TLR4−/− mice during the development of the obesity or diabetes models confirmed that the innate immune receptor TLR4 plays an important role in glycolipid metabolism." (PMID 38275739, 2024). "This process activates TLR-4-mediated immune responses, exacerbating the inherent inflammatory cascades of obesity." (PMID 39282561, 2024). "During obesity, TLR2 and TLR4 are particularly associated with inflammation-associated insulin resistance." (PMID 38397072, 2024). "This study elucidated that AAPs improve obesity by regulating gut microbiota and TLR4/JNK signaling pathway, offering novel perspectives for further conclusion of the anti-obesity potential of AAPs." (PMID 39275156, 2024). "Pathogenic and pathobiont microorganisms increased in obesity interact with TLR receptors, such as TLR-4 and TLR-5." (PMID 39593945, 2024). "The objective of this study is to investigate the inhibitory effects of blocking TLR4 on hyperglycemia and hyperlipidemia by comparing WT and TLR4−/− mice in obesity and diabetes modeling." (PMID 38275739, 2024). "We have already shown that excess free fatty acids produced by increased lipolysis after obesity can lead to a chronic low-grade inflammatory state through activation of TLR4/9." (PMID 38424257, 2024). "Obesity induced in rats via a high-fat diet resulted in alterations in IM composition and activation of Toll-like receptor 4 (TLR4) in the intestinal epithelium." (PMID 38474087, 2024). "Obviously, TLR4 knockout alleviated these changes and reduced the modeling efficiency of high-fat diet-induced obesity or STZ-induced diabetes." (PMID 38275739, 2024). "Increased plasma LPS, a component of the bacterial cell wall, has been shown to mediate obesity-induced metabolic dysregulation by binding to Toll-like receptor 4 (TLR4)." (PMID 39768360, 2024). "Human and animal studies showed increased expression of TLR4 in adipocytes, hepatocytes, muscle and the hypothalamus due to obesity." (PMID 38397072, 2024). "In the obesity model, a high-fat diet can induce chronic low-grade inflammation by activating the TLR-4/NF-κB pathway, representing a crucial mechanism behind metabolic disorders associated with obesity." (PMID 39759101, 2024). "So far, both LPS and long-chain fatty acids, which increase with obesity, have been thought to activate TLR4 expressed on microglia in the induction of hypothalamic chronic inflammation as the underlying mechanism." (PMID 38317079, 2024). "The activation of TLR genes, particularly TLR4, plays a pivotal role in obesity by regulating protein phosphorylation and promoting the production of TNF-α, IL-6, leptin, resistin, and chemokines." (PMID 39733798, 2024). "The present study supports the anti-inflammatory potential of purslane extract for modulating bowel inflammation under obesity through inhibition of the TLR4/NF-κB signaling pathway." (PMID 39845784, 2024). "Toll like receptor (TLR-4) and monocyte chemoattractant protein-1 (MCP-1) have been reported to be a novel adipocytokine involved in the development of obesity-associated insulin resistance and atherosclerosis." (PMID 38755663, 2024). "The toll-like receptor 4 (TLR4) signaling pathway is a major trigger of inflammatory responses stimulated by obesity." (PMID 39845784, 2024).
Obesity (continued). "The adipokine TSP1 has been shown to have a role in the pathophysiology of the obesity-related inflammation via activation of the TLR4 signaling pathway." (PMID 37964189, 2023). "Blood FAs are associated with obesity and are associated with chronic inflammation through increased CD36, TLR4, and NF-κB p65 in monocytes." (PMID 37403139, 2023). "This study found that, compared to the normal weight group, the obesity group expressed higher TLR4, CD36, and NF-κB p65 in monocytes; the obesity group expressed higher TLR4 and CD36 in lymphocytes; and the obesity group expressed higher CD36 in granulocytes." (PMID 37403139, 2023). "TLR receptors were discovered in pancreatic islet cells, and TLR4 is upregulated in response to high glucose levels as well as obesity." (PMID 37830554, 2023). "LPS−activated TLR4 increases intestinal permeability and induces a chronic subclinical inflammatory process, leading to insulin resistance and obesity." (PMID 37239422, 2023). "Under the conditions of a high fat diet, functional TLR4 is one of the necessary conditions to induce obesity." (PMID 37571378, 2023). "As the LPS–toll‐like receptor 4 (TLR4) signaling axis is a central regulator of systemic inflammation, we examined if the effects of diet‐induced obesity on ischemic injury are mitigated by TLR4 knockout (KO)." (PMID 37287396, 2023). "It was demonstrated that TLR4 contributes to the development of IR and inflammation in obesity via its activation by excess enteric lipopolysaccharide (LPS) and SFAs as well as via endogenous ligands, e.g., FFAs." (PMID 37372966, 2023). "Silencing TLR4 increases insulin resistance and reduces inflammation in murine models of diet-induced obesity." (PMID 38276294, 2023). "G. lucidum polysaccharides improve dysbiosis of the gut microbiota and maintain intestinal barrier function to inhibit TLR4/Myd88/NF-κB signaling pathway expression in adipose tissue, thereby exerting treatment of obesity." (PMID 36936157, 2023). "It is being used to observe how this particular EVOO component reverses inflammatory parameters (elevated TNF-, IL-1, and IL-6) and inhibits the activation of TLR-4 and NK-kB pathways, which are related to intestinal permeability in obesity." (PMID 36837428, 2023). "Improved TLR4 mRNA expression was seen in the adipose tissue of obese db/db mice, suggesting a possible role for TLR4 signaling in both obesity and inflammation." (PMID 36674680, 2023). "It is further found that polyphenols can inhibit the overexpression of inflammatory mediators through the TLR4 pathway, and obesity is known to belong to chronic low-grade inflammation." (PMID 37571378, 2023). "The link between leptin and CD14 has also been supported by others that found leptin induces CD14/TLR4 activation by the JAK2-STAT3 signaling pathway to promote obesity-related osteoarthritis." (PMID 37447395, 2023). "One of this study’s attractive findings was the link between a higher obesity incidence and the TT genotype of TLR4 rs1928295." (PMID 37571378, 2023). "Previous studies have identified an inflammatory response and upregulation of TLR4 in IR, obesity, and T2DM." (PMID 37830554, 2023). "Additional research employing animal models, specifically toll-like receptor-4 (TLR4) mutant mice with impaired mucosal immunity, has elucidated the relationship between LPS and obesity." (PMID 37503494, 2023). "According to the findings of this research, the protective effect of vitamin D and exercise against obesity and HFD-induced hepatic steatosis is associated with the downregulation of FATP4 and TLR4, as well as a reduction in inflammation." (PMID 36360622, 2022). "We previously showed that the elevated adipose gene expression of TLR4, TLR2, and MyD88 in people with obesity/T2D was associated with the IRAK1 gene expression." (PMID 36552771, 2022).
Obesity (continued). "Phytochemicals with α, β-unsaturated carbonyl groups including withaferin A, kaempferide, isoliquiritigenin and curcumin were reported to ameliorate obesity and related metabolic symptoms by the suppression of TLR4." (PMID 35769384, 2022). "Since TLR4 mediates LPS pro-inflammatory effects, there appears to be a correlation between the bacteria-related pro-inflammatory stats in the gut and the obesity development induced by diet." (PMID 36056976, 2022). "TLR family plays a fundamental role in the activation of DCs in OA, especially TLR4, promotes obesity-induced OA in the mouse model." (PMID 35860250, 2022). "By activating Toll-like receptor 4 (TLR4), these GAGs contribute to the inflammatory state and consequently the propensity for HCC development, especially in the presence of underlying obesity and diabetes." (PMID 35454809, 2022). "On the other part, resveratrol has been found to alleviate obesity-induced skeletal muscle inflammation due to a shift in macrophage toward an anti-inflammatory profile and a decrease in TLR4 expression." (PMID 36235130, 2022). "In the placental tissues, the obesity group had higher concentrations of LPS, TLR4, and caspase-3 and lower concentration of BCL-2." (PMID 35600958, 2022). "Our findings prove that TLR2 negatively regulates adipocyte differentiation and that TLR2 and TLR4 play opposing roles in the development of mature onset obesity in mice." (PMID 36555322, 2022). "In aged mice, genetic deletion of TLR4 prevented the development of OA from high-fat diet-induced obesity." (PMID 35860250, 2022). "By stimulating the growth of SCFA-producing bacteria, berberine prevents obesity and insulin resistance through the TLR4 signaling pathway." (PMID 35745227, 2022). "As addressed above, substantial evidence has demonstrated the role of TLR4 in obesity-induced adipose tissue inflammation." (PMID 35490239, 2022). "HMGB1 acts as an innate pro-inflammatory mediator in WAT of patients with obesity by binding to TLR4 and triggering an inflammatory response." (PMID 35406022, 2022). "We provided evidence that adipocyte-derived saturated fatty acids (SFAs) activate macrophage TLR4 signaling pathway, thereby forming a vicious cycle of inflammatory responses during the development of obesity." (PMID 35490239, 2022). "Increased level of TLR4 and NF-κB is another signaling pathway manifested in obesity induction due to BPA exposure." (PMID 35328389, 2022). "AT macrophages are activated via TLR4 by LPS which is elevated in obesity, potentially due to alterations in the gut microbiota, dubbed metabolic endotoxemia." (PMID 35348641, 2022). "Studies have revealed that abnormalities in TLR4 and TLR2 are associated with cardiovascular and cerebrovascular diseases, obesity, diabetes, tumors, and metabolic diseases." (PMID 36496853, 2022). "Campferol, which is present in tea leaves, improves the integrity of the intestinal barrier and inhibits inflammation in the intestines by reducing the activation of the TLR4/NF-κB pathway, and prevents the obesity-related gut dysbiosis." (PMID 35745227, 2022). "First, the TLR4 pathway, which is activated by saturated fatty acids, is one of the primary triggers for obesity-induced inflammation." (PMID 35784579, 2022). "The TLR4 signaling pathway is considered to be a main trigger of obesity-induced inflammation, and the TLR4/NF-κB signaling pathway is an important mechanism that regulates the chondrocyte OA inflammatory response." (PMID 35571243, 2022). "Concordant with our results, Mona’s recent study demonstrated that sitagliptin suppresses inflammation by decreasing HMGB1-mediated TLR4/NF-κB signalling in a rat obesity model." (PMID 35163991, 2022). "It was discovered that lowering the activity of these three microorganisms suppresses the TLR4/NF-κB pathway, which prevents the development of prediabetic obesity and colorectal cancer." (PMID 35662727, 2022).
Obesity (continued). "TLR2 and TLR4 are key markers of inflammation in the context of obesity since they bind microbial products as LPS or peptidoglycan (PGN) and fatty acids (FAs) that are present at higher levels in the plasma of obese subjects." (PMID 36010611, 2022). "Microglial ER stress and TLR4 signaling play a crucial role in the development of inflammation and obesity." (PMID 36188456, 2022). "Inflammation in AT leads to obesity-associated fibrosis, and macrophages play a major role in WAT fibrosis by Toll-Like Receptor 4 (TLR4) activation." (PMID 36361737, 2022). "TLR4, one of the thirteen TLRs identified in mammals, influences symptoms induced by high fat diet-induced obesity, including insulin resistance, inflammation, and hepatic lipid accumulation." (PMID 35769384, 2022). "GFPA exhibited strong anti-obesity effects via the modulation of chronic inflammation through Toll-like receptor 4/nuclear factor kappa-B signaling, which supports the use of GFPA for the treatment of obesity." (PMID 35967316, 2022). "Given that NAFLD is accompanied by obesity, and considering that the known impacts of TLR4 signaling in high-fat-induced metabolic disarrangements, we therefore examined obesity-related parameters in HFD-fed mice in the presence of CLI-095 treatment." (PMID 36132991, 2022). "Palmitic acid was chosen as our initial stimulus because it is the most common saturated fatty acid in the human body, is elevated in individuals with obesity due to lipolysis, and it activates TLR4, a receptor that can promote innate immune memory." (PMID 36713396, 2022). "The TLR4 signaling pathway is acknowledged to be one of the main triggers of the chronic low-intensity inflammatory response that is induced by obesity." (PMID 35276992, 2022). "Obesity-induced inflammation is mostly triggered by the TLR4 signaling pathways, and it leads to the production of TNF-α pro-inflammatory cytokines." (PMID 36360622, 2022). "IL-6 is a very promising therapeutic target for obesity, and acupuncture is likely to modulate inflammation and thus affect obesity through the TLR4/NF-κB/IL-6 signaling pathway." (PMID 36105933, 2022). "The low-grade chronic inflammation state in obesity is also responsible for impairment in skeletal muscle glucose uptake by activating TLR-4 and TNF-α." (PMID 35683979, 2022). "Previous studies have reported that in astrocytes, TLR4 signaling plays an essential role in obesity pathogenesis and inflammation." (PMID 36188456, 2022). "The body weight curve of TLR2−/−-TLR4−/− mice resembled that of TLR4−/− mice, indicating that the obesity developed by TLR2−/− mice depends on the expression of TLR4." (PMID 36555322, 2022). "Western blot was applied to detect the TLR4 level, which showed higher concentration in the obesity group." (PMID 35600958, 2022). "Regulatory mechanisms of innate immune responses based on fatty acid chains of sphingolipids are summarized in this review, with focus on ganglioside GM3 and TLR4, and pathogenesis of obesity and metabolic syndrome." (PMID 35712350, 2022). "A potential mechanism of proinflammatory activity can involve the Toll-like receptor 4 (TLR4) which is the main signaling pathway that triggers the obesity-induced inflammatory response." (PMID 36140306, 2022). "Lipopolysaccharide (LPS) secreted from intestinal flora induces chronic subclinical inflammation and obesity through activation of Toll-like receptor 4 (TLR4), leading to IR." (PMID 35455732, 2022). "At the same time, the ELISA method was used to detect TLR4 expression, which showed that the content in the obesity group was significantly higher than that in the control group." (PMID 35600958, 2022). "Circulating LPSs induce a potent inflammatory state through the Toll-like receptor 4 (TLR4) signaling pathway, which is involved in the development of metabolic diseases, such as obesity, insulin resistance, and cardiovascular disease." (PMID 36398438, 2022).
Obesity (continued). "COVID-19, Irisin, Exercise, Sedentarism/Aging, and Obesity influence related inflammatory pathways: TLR4, MyD88, MAPK, AMPK, NF-kB, and cytokine production." (PMID 35784579, 2022). "Resveratrol inhibits the development of obesity-related OA through toll-like receptor 4 (TLR4) and the PI3K-Akt signaling pathway." (PMID 35093162, 2022). "S100A9 overexpression in obesity impaired macrophage differentiation via TLR4-NFkB signaling, worsening inflammation and wound healing." (PMID 35935235, 2022). "The effects of other antipsychotics on astrocytes, ER stress, and TLR4 signaling, as well as their role in antipsychotic-induced obesity, are controversial." (PMID 36188456, 2022). "Increased LPS has been found to be associated with obesity and insulin resistance by binding to CD14 toll-like receptor-4 (TLR-4) and transforming growth factor-β (TGF-β)-mediated pathways." (PMID 35873174, 2022). "The increase in TLR4 observed in the HF Control group is possibly due to the demonstrated ability of TLR4 signaling in the obesity-induced inflammation." (PMID 33419468, 2021). "The activation of TLR4 by free fatty acids, elevated in obesity, generates proinflammatory signals and activation of NF-κB that inhibits the transmission of the insulin signal." (PMID 33520042, 2021). "TLR4, a modulator of innate immunity, contributes to obesity-related OA pathogenesis via mediating metabolic inflammation and cartilage catabolism in OA joints." (PMID 34457118, 2021). "It has been demonstrated that TLR4 regulates obesity-induced inflammation and lipogenesis; for this reason, we explored the lipid profile after the consumption of HFS diet or bioactive foods." (PMID 35010897, 2021). "We also observed an overexpression of the TLR4 gene in the caecum, enforcing the argument that the 2HFD-induced change in the gut microbiota exacerbates inflammation and obesity in mice via the TLR4 signaling pathway." (PMID 33477939, 2021). "As toll-like receptor 4 (TLR4) plays an important role in innate immunity, we investigated the effect of TLR4 knockout (T4KO) in a high-fat high-sucrose diet-induced obesity mouse model." (PMID 33800867, 2021). "TLR4 is the pattern recognition receptor most closely related to obesity in current research, and it is usually upregulated in animal models induced by a high-fat diet and is accompanied by enhanced downstream signaling pathways, such as NF-κB signaling." (PMID 34760017, 2021). "Obesity increases the level of TLR4 protein in the liver, which induces degradation of IκB and dissociation of NF-κB." (PMID 34094031, 2021). "It has been established that TLR4 in particular is both present and active in human skeletal muscle, and observations have shown increased expression in both subjects with obesity and/or T2D21,22,24." (PMID 34930972, 2021). "Obesity is a complex and multifactorial disease, which can lead to an inflammatory condition triggered by the toll-like receptor 4 (TLR4), with a role in the etiology of cardiovascular diseases." (PMID 33925692, 2021). "Besides, clinically used therapeutic agents that are used to control excessive inflammation by inhibiting TLR4 signaling may be developed as obesity-associated CRC therapeutics, these include TAK-242, Candesartan, Valsartan, Fluvastatin, Simvastatin and Atorvastatin." (PMID 34385421, 2021). "Activation of TLR4 signaling pathways triggered by LPS plays a predominant role in obesity-induced inflammation." (PMID 34675215, 2021). "Particularly, TLR2 and TLR4 play a key role in obesity-related inflammation, IR, and vascular dysfunction." (PMID 34445644, 2021). "A meta-analysis including 17 animal studies concludes that chronic endurance exercise leads to a marked tendency towards TLR4 downregulation in macrophages and other immune cells in rodents with obesity or metabolic syndrome." (PMID 34975827, 2021).